GSTK1 (glutathione S-transferase kappa 1)
Description:
Glutathione S-transferase that catalyzes the conjugation of glutathione to exogenous and endogenous compounds. Significant glutathione conjugating activity is found only with the model substrate, 1-chloro-2,4-dinitrobenzene (CDNB).
Synonyms: hGSTK1; GST13; GST; GST 13-13; GST13-13; GSTK1-1
Tractability: Small molecule: a structure with a bound ligand is known; it has a high-quality binding pocket; it belongs to a druggable protein family. PROTAC: ubiquitination databases record sites on it; its protein half-life has been measured; a small molecule that binds it is known.
Target class: Enzyme; Transferase
Gene: Protein-coding gene on chromosome 7 (143,244,093 to 143,270,873, forward strand). Ensembl gene ENSG00000197448.
Subcellular location: Peroxisome
Subcellular location (Human Protein Atlas): Peroxisomes
Pathways (Reactome):
Metabolism: Glutathione conjugation
Protein localization: Peroxisomal protein import
Gene Ontology:
Molecular function: glutathione peroxidase activity; glutathione transferase activity; protein binding; oxidoreductase activity
Biological process: epithelial cell differentiation; glutathione metabolic process; cellular oxidant detoxification; liver development; response to arsenic-containing substance; response to manganese ion
Cellular component: extracellular exosome; membrane; mitochondrion; peroxisome; cytosol; mitochondrial matrix; peroxisomal matrix; cytoplasm
Genetic constraint (gnomAD): Loss-of-function variants: 21 observed, 26.97 expected, observed/expected ratio (o/e) 0.78, 90% interval 0.55 to 1.12. The upper end of that interval is the gene's LOEUF score, 1.12, which puts it in group 4 of 6, group 1 being the genes least tolerant of losing a copy. Missense variants: 284 observed, 295.88 expected, observed/expected ratio (o/e) 0.96, 90% interval 0.87 to 1.06. Synonymous variants: 105 observed, 111.25 expected, observed/expected ratio (o/e) 0.94, 90% interval 0.81 to 1.11.
Homologues: Orthologues: chimpanzee GSTK1 (99% identical), chimpanzee GSTK1 (94% identical), dog GSTK1 (85% identical), guinea pig GSTK1 (79% identical), mouse Gstk1 (71% identical), rat Gstk1 (69% identical), pig GSTK1 (67% identical), tropical clawed frog gstk1 (57% identical), zebrafish gstk1 (50% identical), zebrafish gstk2 (44% identical), zebrafish si:dkey-40m6.14 (44% identical), zebrafish gstk4 (41% identical), and 2 more.
Diseases named in the same sentence as GSTK1 in open-access papers:
GSTK1 is named in the same sentence as 35 diseases in open-access papers, as found by Europe PMC text mining. Sharing a sentence is not in itself a finding about the gene and the disease. The quoted sentences say what the papers report.
breast carcinoma (4 papers, 2021 to 2023). "Higher expression of GSTK1 predicted the longer survival of patients with LumB breast cancer because GSTK1 is associated with decreased reactive species and oxidative stress." (PMID 36936420, 2023). "On the other hand, fat-specific GSTK1 overexpression shields mice from diet-induced obesity, insulin resistance, and hepatic steatosis, and increased GSTK1 levels have been linked to colon cancer progression and improved survival in patients with luminal B breast cancer." (PMID 37371965, 2023). "Patients with breast cancer and sarcomas with low GSTK1 expression had worse prognoses." (PMID 36936420, 2023). "Altered levels of GSTK1 may influence the incidence and development of several cancers, including breast cancer, sarcoma, and prostate cancer." (PMID 36936420, 2023). "GSTK1 expression in HNSC, BRCA, LUSC, and THCA tumors was significantly lower than in normal tissues, which was consistent with previous studies on sarcoma and breast cancer." (PMID 36936420, 2023).
Obesity (4 papers, 2017 to 2026). Accumulation of substantial excess body fat. "Gstk1 is related to oxidative stress, and its expression is negatively correlated with obesity and hypertrophic cardiomyopathy." (PMID 41526530, 2026). "From a macro perspective, a lack of GSTK1 has been linked to hypertrophic cardiomyopathy in zebrafish and diabetic renal tubular injury, subclinical glomerular disease, and obesity-induced inflammation and insulin resistance in mice." (PMID 37371965, 2023). "GSTK1 and GSTO1 are glutathione transferases that play an important role in inflammatory processes such as obesity, insulin resistance, and lipid peroxidation induced by high‐fat diets." (PMID 38894980, 2024).
glioma (3 papers, 2021 to 2024). A benign or malignant brain and spinal cord tumor that arises from glial cells (astrocytes, oligodendrocytes, ependymal cells). "Our results demonstrate that the knockdown of GSTK1, an antioxidant enzyme, robustly inhibited the cell viability of glioma cells." (PMID 38540734, 2024). "Finally, our validation reveals that the elevated expression of GSTK1, an antioxidant enzyme within the signature, promotes the cell growth and migration of glioma cells, with this effect dependent on the peroxisomal targeting signal recognized by PEX5." (PMID 38540734, 2024). "Furthermore, the analysis of patient data from the TCGA, CGGA_693, and CGGA_325 glioma cohorts revealed that individuals with a high expression of GSTK1 experienced reduced survival times." (PMID 38540734, 2024). "Especially, in silico analysis of glioma tissues of the multidimensional data set from TCGA revealed that CD147 are broadly positive associated with Nrf2 target genes regulating redox homeostasis, including NQO-1, HO-1, GSTK-1, and GSS, which further confirmed the CD147 regulation of Nrf2." (PMID 34421346, 2021).
Insulin resistance (3 papers, 2023 to 2025). Increased resistance towards insulin, that is, diminished effectiveness of insulin in reducing blood glucose levels. "Glutathione S-transferase kappa 1 (GSTK1) is specifically localized to mitochondria and peroxisomes, participates in adiponectin secretion and insulin resistance, and inhibits the progression of non-alcoholic fatty liver disease." (PMID 41276823, 2025).
colon cancer (2 papers, 2023). "In the human digestive system, the expression of CYP2E1 and GSTK1 was found to be higher in both the gastric and colon tumor tissues." (PMID 36766250, 2023).
diabetic cardiomyopathy (2 papers, 2016 to 2025). Diabetic cardiomyopathy is a disorder of the heart muscle in people with diabetes. "Proteomic analysis revealed that Gstk1 expression is decreased in HCM caused by pressure overload and diabetic cardiomyopathy." (PMID 27378925, 2016). "Notably, GSTK1 and UGT2B subfamily members co-regulate Chemical carcinogenesis-DNA adducts, Drug metabolism-Cytochrome P450, and extracellular exosome signaling, while IDH1/SDHB/SDHD link TCA cycle defects to redox imbalance in diabetic cardiomyopathy and tumorigenesis." (PMID 40626307, 2025).
sarcoma (2 papers, 2022 to 2023). A usually aggressive malignant neoplasm of the soft tissue or bone. "Prior studies found that GSTK1 is related to the tumorigenesis of breast, sarcoma, and prostate tumors." (PMID 36936420, 2023).
Bladder urothelial carcinoma (1 paper, 2023). "Low GSTK1 expression was associated with worse overall survival in Bladder urothelial carcinoma, Kidney renal papillary cell carcinoma, BRCA, and HNSC." (PMID 36936420, 2023).
delirium (1 paper, 2025). A disorder characterized by confusion; inattentiveness; disorientation; illusions; hallucinations; agitation; and in some instances autonomic nervous system overactivity. "Meanwhile, higher expression ofSCP2,DMPK,GSTK1, andSIRT3might increase the risk of delirium." (PMID 41330563, 2025). "There were eight protective genes (DHODH,DHRS7B,TOP1MT,CASP8,GFM1,CPT1B,TK2,GPD2), and four genes (SCP2,DMPK,GSTK1,SIRT3) that increased delirium risk, as shown inFigure 2, withp = 0.05 (dotted line); and false discovery rate (FDR) < 0.05 (red asterisks)." (PMID 41330563, 2025).
diabetes type 2 (1 paper, 2019). "GSTK1 was shown to be associated with diabetes type 2 which is another major aging related disease." (PMID 30975078, 2019).
erythroleukemia (1 paper, 2021). Acute erythroid leukemia characterised by the presence of at least 50% erythroid precursors and at least 20% myeloblasts in the bone marrow. "In fact, GSTK1 was predominantly expressed in many types of tumor cells and regarded as its marker protein, including oral premalignant and malignant lesions and human erythroleukemia." (PMID 34557266, 2021).
head and neck squamous cell carcinoma (1 paper, 2023). A squamous cell carcinoma that arises from any of the following anatomic sites: lip and oral cavity, nasal cavity, paranasal sinuses, pharynx, larynx, and salivary glands. "However, the clinical significance of GSTK1 in head and neck squamous cell carcinoma (HNSC) remains unclear." (PMID 36936420, 2023).
Infertility (1 paper, 2023). "Next, we investigated whether the selected candidates, GSTP1, GSTO2, and GSTK1, played important roles in the observed infertility caused by decreased Klotho expression." (PMID 37759974, 2023). "After analysis of the published dataset (GSE6872,), the mRNA levels of GSTP1, GSTO2, and GSTK1 were remarkably reduced in sperm from infertile men, who had severe sperm morphological defects, compared to sperm from fertile individuals." (PMID 37759974, 2023).
pancreatic cancer (1 paper, 2025). "The results revealed that in pancreatic cancer patients (n = 89), high GSTK1 expression was significantly associated with shorter overall survival (OS) (HR = 1.6, p = 0.027, p(HR) = 0.029)." (PMID 40963930, 2025). "Notably, elevated GSTK1 expression has been associated with poorer prognosis in pancreatic cancer patients and has been strongly positively correlated with the C4 malignant subpopulation signature." (PMID 40963930, 2025).
primary immunodeficiency (1 paper, 2023). "GSTK1 expression was positively enriched in immune infiltration pathways, including primary immunodeficiency (PID), immunoregulatory interactions between lymphoid and non-lymphoid cells (IGI), and interferon gamma signaling (IFN-γ)." (PMID 36936420, 2023).
prostate adenocarcinoma (1 paper, 2023). "A study using transgenic prostate adenocarcinoma in mice showed that low levels of GSTK1 were associated with hypermethylation, which affects tumorigenesis." (PMID 36936420, 2023).
sarcopenia (1 paper, 2025). Progressive decline in muscle mass due to aging which results in decreased functional capacity of muscles. "The findings demonstrated that, in comparison to other variables, the expression of the SMGs gene GSTK1 had a substantially increased influence on the Sarcopenia diagnostic model." (PMID 41325398, 2025). "LASSO regression identified CTH and IDI1 for IPF, and FOXO1, CTH, HSD11B1, GSTK1, and SPTSSA for sarcopenia." (PMID 41325398, 2025). "The findings demonstrated that FOXO1, CTH, HSD11B1, GSTK1, and SPTSSA were the five sarcopenia model genes (SMGs) that were included in the LASSO regression model." (PMID 41325398, 2025). "In general, the validity of the diagnostic models was evident with the values of the predictive models of IPF; CTH, and IDI1 as well as the models of sarcopenia; FOFOXO1, CTH, HSD11B, GSTK1, and SPTSSA." (PMID 41325398, 2025).
schizophrenia (1 paper, 2025). A major psychotic disorder characterized by abnormalities in the perception or expression of reality. "The genotype rs1917760*T/T GSTK1 was linked to a higher BMI score in male schizophrenia patients, while in female patients this genotype was associated with a lower BMI score." (PMID 40732231, 2025). "Schizophrenia patients with the GSTK1 rs1917760*T allele or GSTM1 deletion had a higher risk of being overweight." (PMID 40732231, 2025).
tumor (7 papers, 2020 to 2025). "RNA-sequence and non-target metabolomics analysis were employed to further explore the function of GSTK1 and elucidate the molecular mechanism underlying GSTK1 on the tumor malignant phenotype." (PMID 41276823, 2025). "Apparently, the levels of GSTK1 mRNA and protein were decreased in tumors compared to para-tumor tissues." (PMID 41276823, 2025). "Bexarotene promoted apoptosis of tumor cells, while GSTK1 overexpression further increased the apoptosis ratio." (PMID 41276823, 2025). "Human HCC cell lines with GSTK1 overexpression or knockdown were used to determine GSTK1 function in tumor growth and migration in vitro." (PMID 41276823, 2025). "Patients with low GSTK1 expression were more likely to have poor overall survival [OS] (P = 0.002) and early tumor recurrence (P = 0.025)." (PMID 41276823, 2025). "IF and IHC staining showed that lower GSTK1 expression in tumor tissues had higher expression of p-DRP1 (Ser616) or lower CPT2, CACT, and BBOX." (PMID 41276823, 2025). "We therefore plan to perform experiments to evaluate the benefits of drugs targeting GSTK1 methylation on cancer model survival and tumor growth inhibition." (PMID 36936420, 2023). "GSTK1, which is known as a tumor marker, showed some kind of relationship with cancer cell proliferation." (PMID 34557266, 2021). "In addition, tumor cell ATP production decreased after GSTK1 overexpression and increased following GSTK1 knockdown." (PMID 41276823, 2025). "Additionally, we reveal that an mTOR inhibitor can increase tumor cell sensitivity to radiation-induced damage by downregulating GSTK1 expression, thereby weakening glutathione-mediated ROS clearance." (PMID 40963930, 2025). "GSTK1 was shown to be a tumor suppressor via its role in MQC and L-carnitine metabolism." (PMID 41276823, 2025). "We divided the tumor samples into two groups according to GSTK1 expression and found that Cytotoxic cells and T cells infiltration were positively correlated with the level of GSTK1 (p < 0.001)." (PMID 36936420, 2023). "We also tried to determine whether the tumor immune micro-environment was different in HNSC patients with low GSTK1 levels compared with those with high expression levels." (PMID 36936420, 2023). "GSTK1 expression in pairs of tumor and para-tumor tissues from HCC patients was examined using RT-qPCR, western blot analysis, and IHC to determine the clinical relevance of GSTK1 in HCC." (PMID 41276823, 2025). "In order to verify GSTK1 expression correlation with Cytotoxic cells (CD8) and T cells (CD3) infiltration, we detected GSTK1, CD8 and CD3 expression in tumor samples." (PMID 36936420, 2023). "The expression of GSTK1 protein in BLCA and KIRP in tumor tissues was the same as in adjacent tissues, which was contrary to the results obtained from the TIMER database." (PMID 36936420, 2023). "To further investigate the role of GSTK1 in HNSC, we initially proved that the expression of GSTK1 in HNSC tumor specimens was lower than that of normal para-carcinomatous tissues." (PMID 36936420, 2023). "In addition, GSTA1, GSTM1, and GSTZ1 are reported to be downregulated in tumor tissue and can correlate with a poor prognosis, while GSTT1, GSTO1, and GSTK1 are mostly reported to be upregulated in tumor tissue compared to the normal surrounding tissue." (PMID 33228209, 2020).
cancer (6 papers, 2021 to 2025). A tumor composed of atypical neoplastic, often pleomorphic cells that invade other tissues. "To finesse this approach to target particular GST isoforms in the context of cancer, here we have determined the kcat/Km for the human isoforms of GSTK1-1, GSTA1-1 and GSTA4-4 with respect to GSH and CDNB." (PMID 38593670, 2024). "Based on our analysis of the TIMER database, GSTK1 had inconsistent mRNA expression in the 34 types of human common cancer." (PMID 36936420, 2023). "The prognostic value of GSTK1 expression in human cancers was analyzed using the Kaplan-Meier plotter database and the HPA database." (PMID 36936420, 2023). "The present work compared the expression GSTK1 in normal tissue versus human cancers to determine if it is potential prognostic cancer biomarker." (PMID 36936420, 2023). "Some of them have been reported as biomarkers in other types of cancers, such as GSTK1, IDH2, CAVIN3, HMGCS2, and ACOX1." (PMID 34557266, 2021). "This information suggests that a comprehensive analysis of GSTK1 expression in cancer is necessary." (PMID 36936420, 2023). "First, the expression of GSTK1 in human cancers was comprehensively analyzed." (PMID 36936420, 2023). "The expression of GSTK1 in various cancers was explored with TIMER and TCGA databases." (PMID 36936420, 2023). "Many GSTs, e.g., GSTO1, GSTP1, GSTK1, GSTA4 and GSTM3, are reported to cause resistance in cancer." (PMID 36428646, 2022). "However, associations between GSTK1 expression and prognosis have not been well described in other cancer types." (PMID 36936420, 2023). "Notably, we previously showed that top genes of this program (LDHB, GSTK1, DGKA, APRT, MGAT4A, and NMRK1) are predictive of the response of patients with cancer to ICIs." (PMID 40187353, 2025).
GSTK1 also shares sentences with these, for which no sentence is quoted: hypertrophic cardiomyopathy (3 papers); Esophageal stricture (1); Hepatic steatosis (1); hepatoblastoma (1); infarction (1); infection (1); influenza (1); ischemia (1); lung carcinoma (1); Lung squamous cell carcinoma (1); non-alcoholic fatty liver disease (1); ovarian carcinoma (1); prostate tumors (1); Renal cyst (1); Thyroid carcinoma (1).